IL6 (interleukin 6)
Diseases named in the same sentence as IL6 in open-access papers (continued):
Sharing a sentence is not in itself a finding about the gene and the disease.
atherosclerosis (continued). "Several pro-inflammatory mediators and adhesion molecules implicated in the progression of atherosclerosis, including hsCRP, IL-6, sVCAM-1, sICAM-1, P-selectin, E-selectin and ADMA, are elevated in HIV-infected patients." (PMID 24594990, 2014). "By contrast, circulating concentrations of novel CVD risk biomarkers including interleukin-6 and interleukin-5 adipokines were mostly similarly associated with both endothelial activation and atherosclerosis amongst African black and white RA patients." (PMID 25157371, 2014). "Growth differentiation factor-15 deficiency inhibits the progression of atherosclerosis by controlling the interleukin-6-dependent inflammatory response to vascular injury." (PMID 25318463, 2014). "Tumor necrosis factor-α (TNF-α) has been implicated in myocardial dysfunction resulting from acute coronary syndrome and high levels of C-reactive protein and IL-1 and IL-6 have been associated with subclinical atherosclerosis." (PMID 25374442, 2014). "IL-6 is associated with lipid metabolism and plays a role in the development of atherosclerosis through a number of different mechanisms causing metabolic and endothelial dysfunction." (PMID 23698162, 2013). "Fourth, chronic infectious burden and elevated inflammatory markers, such as C-reactive protein and interleukin-6, have been associated with the development of atherosclerosis and increased risk of stroke." (PMID 24023710, 2013). "Proinflammatory cytokines such as interleukin (IL)-6 and IL-1 are associated with development and progression of atherosclerosis; furthermore, new soluble markers including osteoprotegerin (OPG) have been shown to be involved in this process." (PMID 24383040, 2013). "It is IL-6R ‘trans-signalling’, where IL-6 binds to soluble forms of IL6-Rα (sIL6-Rα) and triggering hyperactivation of gp130, that is thought to underlie the pro-inflammatory actions of IL-6 in a variety of diseases, including atherosclerosis." (PMID 23782265, 2013). "An abnormally high plasma level of IL-6 represents a further risk factor for plaque rupture and atherosclerosis progression." (PMID 24228026, 2013). "IL-6, an inflammation pre-stimulation monokine secreted by mononuclear-macrophages with moderate inflammatory activity, is strongly associated with atherosclerosis and its progression." (PMID 23941539, 2013). "In our study, the use of the synbiotic demonstrated a significant decrease in the concentration of cytokine IL-6, which has been utilized as a marker of cardiovascular risk, accelerated atherosclerosis, and mortality in HIV-infected patients." (PMID 23101545, 2012). "We have shown that chronic arsenic exposure for 12 weeks in adult mice elevates plasma MCP-1 and IL6, both cytokines that are associated with atherosclerosis." (PMID 22719926, 2012). "Overproduction of IL6 has been associated with a spectrum of age-related conditions, including atherosclerosis, peripheral vascular disease, coronary artery disease, and osteoporosis." (PMID 22107760, 2011). "All of these data suggest the significant inverse relationship between level of adiponectin and IL-6 or TNF-α associated with the development of inflammation-related atherosclerosis." (PMID 21829524, 2011). "Elevated levels of IL-6 and intercellular adhesion molecules have been associated with endothelial dysfunction in various pathological conditions, such as atherosclerosis and its complications." (PMID 20181009, 2010). "Several studies have shown that elevated plasma levels of C-reactive protein (CRP), interleukin-6 (IL-6), fibrinogen and other soluble inflammatory mediators are associated with both the severity of atherosclerosis and the risk of CHD." (PMID 19639050, 2009). "Interleukin 6 mediated inflammation is implicated in age-related disorders including Atherosclerosis, Peripheral Vascular Disease, Coronary Artery Disease, Osteoporosis, Type 2 Diabetes, Dementia and Alzheimer's disease and some forms of Arthritis and Cancer." (PMID 17374166, 2007).
atherosclerosis (continued). "Many studies also suggest that smoking induces inflammatory factors (TNF-α, CRP, IL-6, fibrinogen, etc.)that are risk factors for atherosclerosis and cardiovascular diseases." (PMID 16262911, 2005). "Additionally, the presence of high levels of inflammatory markers such as elevated levels of CRP and interleukin-6 (IL-6), has been linked to the progression of atherosclerosis in NCVs." (PMID 41517773, 2026). "Additionally, in contrast to hsCRP, the causal role of both suPAR and IL‐6 with atherosclerosis has been established." (PMID 40619914, 2025). "Notably, IL-6 is implicated in the aging of vascular and myeloid cells, potentially leading to a mutual reinforcement that promotes atherosclerosis." (PMID 40125519, 2025). "The cardiovascular risk presented by DNMT3A- and TET2-mutant CHIP can be mitigated by an inhibitory IL-6 receptor gene variant (IL6R p.Asp358Ala), highlighting the key role of the mediators of inflammation NLRP3, IL-1β and IL6 in CHIP-associated atherosclerosis." (PMID 40076674, 2025). "Elevated IL-6 levels are linked to increased cardiovascular risk and atherosclerosis progression." (PMID 40944256, 2025). "Therefore, it is crucial to investigate how TCZ affects atherosclerosis because IL-6 and CRP are linked to CVD, even in healthy males." (PMID 39897309, 2025). "Pro‐inflammatory macrophages in particular initiate and sustain tissue inflammation by producing inflammatory cytokines such as IL‐6 or TNF‐α,24 among which IL‐6 particularly has been reported to be associated with enhanced inflammation in the context of atherosclerosis." (PMID 39909868, 2025). "It is associated with parameters such as liver IL-6 level, which suggests that gut microbiota might play an indirect role in the pathological process of atherosclerosis by promoting inflammatory responses." (PMID 41244676, 2025). "So, does podocyte injury caused by anti-PLA2R antibody cause increased IL-6 production by podocytes, which in turn promotes atherosclerosis and thrombosis, thus increasing the risk of cardiovascular, cerebrovascular, and thromboembolic events in patients with pMN?" (PMID 39982801, 2025). "Elevated levels of IL-6 are associated with an increased risk of cardiovascular diseases, particularly due to its strong inflammatory properties, which can contribute to the development and progression of atherosclerosis." (PMID 40006011, 2025). "We hypothesized that antagonizing the IL-6 pathway in CHIP carriers will reduce their risk of cardiovascular disease (CVD) since CHIP speeds up atherosclerosis and elevates IL-6/IL-1 expression in mice." (PMID 39844544, 2025). "Theoretically more promising is the IL-6 block, Ziltivekimab, a monoclonal antibody targeting the IL-6 ligand that significantly reduces inflammation and thrombosis biomarkers linked to atherosclerosis." (PMID 39796190, 2025). "Furthermore, p-coumaric acid suppressed the expression of NF-kB, COX-2, tumor necrosis factor-alpha (TNF-α), and interleukin-6 (IL-6), suggesting its potential to mitigate the inflammatory response associated with atherosclerosis." (PMID 41226277, 2025). "Moreover, when the endothelium is damaged, foam cells and smooth muscle cells release IL-6 and other inflammatory cytokines, causing more vascular damage and exacerbating this process, ultimately leading to the formation and progression of atherosclerosis." (PMID 38988836, 2024). "In addition, TNF-α and IL-6 can also promote the formation of foam cells, which increases the risk of atherosclerosis in RA patients." (PMID 38731567, 2024). "Systemic inflammation, a hallmark of atherosclerosis, likely plays a crucial role, with elevated inflammatory markers such as interleukin-6, tumor necrosis factor-α, and highly sensitive c-reactive protein contributing to oxidative stress and endothelial dysfunction." (PMID 39272707, 2024).
atherosclerosis (continued). "Furthermore, elevated IL-6 levels are associated with many age-related conditions, like atherosclerosis, arthritis, dementia and functional decline, all of which are components of FI." (PMID 39764189, 2024). "Notably, cardiovascular disease remains a leading cause of mortality in RA patients, with IL-6 implicated in the development of atherosclerosis." (PMID 39469275, 2024). "Interleukin 6 (IL-6) is a cytokine implicated in the development of atherosclerosis." (PMID 37838929, 2024). "Similarly, IL6 is known for its role in inflammation and is associated with conditions like Crohn’s disease, adenocarcinoma, malignant neoplasms of the breast, and atherosclerosis." (PMID 39337647, 2024). "Furthermore, IL-1 and IL-6 are key cytokines involved in inflammatory processes and have been linked to atherosclerosis progression." (PMID 38540305, 2024). "Attempts to contextualize these two molecules in the setting of atherosclerosis have also implicated the IL-6 class cytokine oncostatin M. However, given the multifactorial nature of atherosclerosis, a direct link between these three effectors is still being investigated." (PMID 38737892, 2024). "During this process, a large number of CD8+ T cells are present, and their secretion of tumor necrosis factor-α (TNF-α) and interleukin-6 (IL-6) causes low-grade systemic inflammation, which is a pathogenic factor for atherosclerosis and cardiovascular diseases." (PMID 38922089, 2024). "Age-related increases in inflammatory molecules, such as interleukin-6 (IL-6) levels, are associated with several pathophysiological processes, including atherosclerosis, osteoporosis, and sarcopenia, as well as functional decline, disability, and all-cause mortality in older adults." (PMID 38339365, 2024). "Additionally, hypomethylation of the IL-6 promoter region was found in coronary heart disease subjects as compared with controls, and DNA hypomethylation in the IL-6 gene is associated with increased IL-6 gene expression in atherosclerosis patients." (PMID 38031118, 2023). "Clone results of bone marrow cells with TET2 mutation showed IL-6 and IL-1 β, which may lead to accelerated atherosclerosis." (PMID 37361203, 2023). "Furthermore, polymorphisms in the IL-6 gene are associated with AS and also act as a promoter of atherosclerosis." (PMID 37509127, 2023). "Consequently, this activation leads to an increase in IL-6 production, which further promotes local inflammation and contributes, in association with macrophage infiltrate, to the progression of atherosclerosis." (PMID 38139349, 2023). "IL-6 is reportedly associated with ageing of both vascular and myeloid cells, which may reinforce each other and promote atherosclerosis." (PMID 38139349, 2023). "The importance of the inflammasome in atherosclerosis development, in addition to its effect on interleukin 1 family, is the downstream activation of the central signaling cytokine interleukin 6 (IL-6), which is associated with the enhanced release of C-reactive protein." (PMID 38067150, 2023). "IL-6 as a mediator of inflammation has been associated with atherosclerosis in RA patients." (PMID 35865390, 2022). "Herein, the exacerbated production of IL-6 is associated with age-related diseases, suggesting that IL-6 plays a pathogenetic role in age-related diseases such as osteoporosis, AD, multiple myeloma, or atherosclerosis." (PMID 35106183, 2022). "Moreover, increased inflammation and the development of vascular disease and atherosclerosis are associated with elevated levels of IL-6 in diabetic individuals." (PMID 35554836, 2022). "Furthermore, proinflammatory cytokines, such as IL-6 and tumor necrosis factor-α, have been implicated in the progression of atherosclerosis and type 2 diabetes." (PMID 35352134, 2022). "Increased IL-6 can accelerate collagen metabolism and cause atherosclerosis." (PMID 35419117, 2022).
atherosclerosis (continued). "Atherosclerosis progression, as a chronic inflammatory mechanism, is characterized by immune system dysregulation associated with increased pro-inflammatory cytokine production, including interleukin 6 (IL-6), tumor necrosis factor-α (TNF-α), and IL-1β." (PMID 36274722, 2022). "Increased plasma IL-6 levels correlates with risk for CAD, furthermore treatment of patients with high atherosclerotic risk with ziltivekimab, a human monoclonal antibody against IL-6, resulted in a reduction of inflammation biomarkers relevant to atherosclerosis." (PMID 36189218, 2022). "IL-6 is also associated with atherosclerosis and cardiovascular disease, which may also be a vital mediator of the inflammatory response in ischemic stroke." (PMID 35887619, 2022). "The increased activity of angiotensin II through the angiotensin II type I receptor (AT1R) can cause inflammation and the release of interleukin-6 (IL-6) and decrease in nitric oxide (NO) activity, causing endothelial dysfunction and increasing the risk of atherosclerosis." (PMID 35885904, 2022). "Atherosclerosis is more frequently encountered in the older population, being linked to changes in both myeloid cell hematopoiesis and vasculature, as these systems share the same inflammatory pathway mediated by IL-6 signaling." (PMID 35456556, 2022). "IL-6 may cause the progression of atherosclerosis by inducing endothelial dysfunction and lipoprotein oxidation, and it is an independent risk factor for coronary artery disease." (PMID 36551255, 2022). "We have shown, using a mouse model with preexisting atherosclerosis exposed to perioperative stress, that IL-6 neutralizing antibodies but not inhibition of its trans-signaling protects plaque stability, proving that IL-6 here is causal for vascular effects of surgical stress." (PMID 35548445, 2022). "Interestingly, relaxin-2 exerts an anti-inflammatory effect by decreasing IL-6 mRNA expression and plasma levels in rat left ventricle and infarcted myocardium as well as in apolipoprotein E-deficient mice model of atherosclerosis." (PMID 35887517, 2022). "In addition, the pro-apoptotic protein Bax and atherosclerosis-associated cytokines (interleukin-1β, interleukin-6, and tumor necrosis factor-α) were significantly downregulated, whereas the anti-apoptotic protein Bcl-2 was upregulated." (PMID 35137664, 2022). "IL-6 may have pro-atherogenic and anti-atherogenic effects on processes associated with the development and progression of atherosclerosis." (PMID 35163364, 2022). "IL-6 is also expressed in human atherosclerotic plaque, and an investigation of the correlation between IL-6 and risk factors of cardiovascular disease in healthy individuals showed that high IL-6 levels were associated with the risk of atherosclerosis-associated MI." (PMID 34071276, 2021). "Also, IL-6 likely contributes causally to atherothrombosis and is associated with atherosclerosis progression." (PMID 33804661, 2021). "Hypertriglyceridemia is linked to atherosclerosis, increased production of pro-inflammatory cytokines including tumor necrosis factor-α (TNFα) and interleukin-6 (IL6), and may alter the function of the blood–brain barrier (BBB)." (PMID 34915908, 2021). "We next measured IL‐6 release, a pivotal cytokine associated with atherosclerosis." (PMID 33936566, 2021). "Studies have demonstrated that an increase in hs-CRP and IL-6 may confer similar risk as conventional cardiovascular risk factors for the incidence and prognostication of myocardial infarction and atherosclerosis." (PMID 34386531, 2021). "IL-6 can cause chronic inflammation and magnify acute inflammatory response to some extent and promote the release of some chemokines and reactive oxygen species to participate in and further aggravate the atherosclerosis process." (PMID 34568579, 2021). "Increased plasma levels of IL-6 are considered as an independent risk factor for atherosclerosis." (PMID 33875621, 2021).
atherosclerosis (continued). "Clinical and experimental evidence suggest causality of IL6 trans-signaling on the inflammatory response in atherosclerosis and data from our group indicate that an excess of the circulating IL6:sIL6R over the ternary IL6:sIL6R:sgp130 complex increases the risk for future cardiovascular (CV) events." (PMID 31932740, 2020). "The generation of intracellular ROS can subsequently activates the redox sensitive transcription factor nuclear factor κB (NF-κB), which modulates the expression of a variety of genes associated with inflammation and atherosclerosis, including interleukin-6 (IL-6)." (PMID 32516877, 2020). "Furthermore, it was shown that TNFα, IL-6 and IL-12 were increased in G2A-deficient macrophages in atherosclerosis." (PMID 32708184, 2020). "Thus, Th22 cell‐derived IL‐22 aggravates atherosclerosis development through a mechanism that is associated with IL‐6/STAT3 activation, DC‐induced Th17 cell proliferation and IL‐22–stimulated SMC dedifferentiation into a synthetic phenotype." (PMID 32022386, 2020). "Gustafson and colleagues reported that, among the fat storage compartments in the body, VAT was found to be an important source of pro-inflammatory adipokines such as TNF-α and IL-6, and it was associated with an increased risk for atherosclerosis, more so than subcutaneous fat." (PMID 32370212, 2020). "The increased inflammatory activity associated with atherosclerosis is partially brought about by increased levels of pro-inflammatory cytokines in the circulation, particularly IL6, which is associated with a twofold increase in CVDs and mortality in elderly patients." (PMID 30414891, 2019). "Notably, activation of the JAK2/STAT3 pathway is closely associated with the IL-6 cytokine family, which plays an essential role in endothelial cell dysfunction during atherosclerosis." (PMID 31588227, 2019). "The IL-6 amplifier is also thought to be associated with a number of diseases and disorders as well as cardiovascular diseases, including atherosclerosis, in patients with OSA, since IH activates both NF-κB (via hypoxic conditions) and STAT3 (via increased IL-6)." (PMID 31159449, 2019). "Indeed, IL-6 has been linked to atherosclerosis and CV disease in the setting of ARDs as well as in the general population." (PMID 31110500, 2019). "Moreover, recent studies support a causal role for IL-6 signaling pathway in atherosclerosis, which is supported by the evidence that modulation of the IL-6 pathway associates with reduced cardiovascular events." (PMID 30558209, 2018). "IL-6 and TNFα are produced chiefly by activated macrophages, and they are known to influence lipid metabolism and regulate the synthesis of other acute phase proteins which are established risk factors for atherosclerosis." (PMID 29801502, 2018). "In type 2 diabetes, IL-6 level was increased and associated with atherosclerosis development." (PMID 28484449, 2017). "However, to further confirm the role of TLR4 ligand-induced IL-6 production in the pathogenesis of atherosclerosis, in vivo studies using TLR4-deficient mice should be conducted in the future." (PMID 27563891, 2016). "Researchers have proved that IL-6 levels at the diabetic persons are significantly higher than the healthy ones and this altitude may be a risk factor for the complications like atherosclerosis." (PMID 26981134, 2016). "The lack of association between CAC and CRP in contrast to ESR and IL-6 indicates that the association between atherosclerosis, calcification, and inflammation is complex and that individual cytokines might represent different pathogenic pathways." (PMID 27648442, 2016). "Notably in the present context, IL-6 concentrations were also shown to be associated with coronary artery calcification scores that represent atherosclerosis, in RA." (PMID 25157371, 2014). "Furthermore, IL-6 is found to be linked with the development of coronary disease and atherosclerosis." (PMID 24586754, 2014).